CD40LG (CD40 ligand)
Diseases named in the same sentence as CD40LG in open-access papers (continued):
Sharing a sentence is not in itself a finding about the gene and the disease.
ischemic stroke (20 papers, 2011 to 2025). A stroke disorder caused by obstruction of blood flow to the brain, due to thrombotic (local blood clot formation) or embolic (due to a blood clot or other material traveling from another site) event. "Studies also highlight the predictive use of MCP-1 and soluble CD40 ligand (sCD40L) as biomarkers in ischemic stroke." (PMID 40949500, 2025). "A study underscored the association between elevated levels of specific inflammatory mediators, such as CD40 ligand (CD40L) and monocyte chemoattractant protein‐1 (MCP‐1), and the risk of long‐term nonfatal vascular events in ischemic stroke patients." (PMID 38323746, 2024).
Nephropathy (20 papers, 2012 to 2025). A nonspecific term referring to disease or damage of the kidneys. "CD40–CD40 ligand (CD154) signaling has been found to enhance vascular inflammation, bowel disease, and nephropathy." (PMID 29073149, 2017).
prostate carcinoma (20 papers, 2000 to 2025). A carcinoma that arises from epithelial cells of the prostate gland. "Stimulation of DC for 24 hours with CD40 ligand (CD154), IL-12 or IL-15 prior to their co-incubation with prostate cancer cells resulted in a significant increase in DC survival in the tumour microenvironment." (PMID 10945499, 2000). "An Ad5-based vector with the therapeutic CD40 ligand transgene driven by the CMV promoter, Ad[CD40L], was studied in prostate cancer cell lines." (PMID 21379379, 2011).
schistosomiasis (20 papers, 2005 to 2025). An infectious disease caused by parasitic trematodes of the genus Schistosoma that colonize human blood vessels and release eggs that can cause granulomatous reactions leading to acute (swimmer's itch or acute schistosomiasis syndrome) or chronic disease. "IL-13 induces proliferation and CD154 (CD40 ligand) expression in lung fibroblasts and is important in inducing fibrosis in Th2 mediated diseases such as schistosomiasis." (PMID 15987480, 2005).
psoriasis (19 papers, 2011 to 2025). An autoimmune condition characterized by red, well-delineated plaques with silvery scales that are usually on the extensor surfaces and scalp. "The LDGs in human SLE and psoriasis interacted with activated platelet via CD40 ligand exacerbating vascular disease, suggesting the potential targeting of platelet." (PMID 34163363, 2021).
Cognitive impairment (18 papers, 2010 to 2025). Abnormal cognition is characterized by deficits in thinking, reasoning, or remembering. "Therefore, PM2.5 may promote the expression of CD40LG, which encodes a protein involved in the inflammatory response, by promoting hypomethylation, thus exacerbating the systemic inflammatory response and increasing the risk of developing cognitive impairment." (PMID 39997934, 2025).
colorectal cancer (18 papers, 1987 to 2025). A primary or metastatic malignant neoplasm that affects the colon or rectum. "Furthermore, high levels of the CD40 ligand (CD40LG) have been associated with poor prognosis in colorectal cancer." (PMID 37654625, 2023). "In the available literature, there is little information regarding the role of sCD40L in colorectal cancer, and it is further believed that the role of the CD40 ligand is not the same in different cancers." (PMID 34441316, 2021).
cryptococcosis (17 papers, 2010 to 2026). An acute or chronic, localized or disseminated infection by Cryptococcus neoformans. "Monogenic mutations, such as those in the zinc transcription factor GATA2 gene, the transcriptional activator STAT3 gene, and the CD40 ligand CD40LG gene, are also associated with cryptococcosis in seronegative HIV patients (39, –, 41)." (PMID 30755511, 2019).
pancreatic cancer (16 papers, 2011 to 2025). "Further analysis showed that the intratumour level of FLT3LG and CD40LG were positively correlated with αDC and tumour-resident DC scores in human pancreatic cancers." (PMID 37433774, 2023). "Patients with X-linked immunodeficiency with hyper-IgM, caused by mutations in the CD40 ligand, have a high incidence of tumors of the pancreas and liver." (PMID 27703456, 2016).
severe combined immunodeficiency (16 papers, 2014 to 2025). Severe combined immunodeficiency (SCID) comprises a group of rare monogenic primary immunodeficiency disorders characterized by a lack of functional peripheral T lymphocytes resulting in early-onset severe respiratory infections and failure to thrive. "The prevalence of T. marneffei infection is particularly high in HIV-uninfected pediatric patients with severe combined immunodeficiencies (SCID), hyperimmunoglobulin (hyper-IgE) syndrome (HIES), CD40LG deficiency, and others." (PMID 39911395, 2025). "Two candidate damage variants were identified in CD40LG and CARD11 genes previously associated with Combined Immunodeficiency (CID)." (PMID 37592284, 2023). "The study included five patients with X-linked agammaglobulinemia (XLA), four patients with Ataxia Telangiectasia (AT), and eight patients with various combined immunodeficiency (CID) diseases; STAT3 deficiency, CD40 ligand deficiency and IL6 receptor deficiency." (PMID 33557365, 2021).
glioma (14 papers, 2013 to 2025). A benign or malignant brain and spinal cord tumor that arises from glial cells (astrocytes, oligodendrocytes, ependymal cells). "Activated platelets can release the CD40 ligand, inhibiting the migration ability of CD4CD25Foxp3 regulatory T cells and eventually affecting the antitumor immunity of gliomas." (PMID 39707577, 2024). "In gliomas, overexpression of CD40LG may promote activation of immunosuppressive microglia, while in LUAD, it enhances recruitment of cytotoxic T cells." (PMID 41048996, 2025).
pemphigus (14 papers, 2015 to 2025). Pemphigus is a group of rare autoimmune diseases that cause blistering of the skin and mucous membranes (mouth, nose, throat, eyes, and genitals).This conditioncan occur at any age, but often strikes people in middle or older age. "A role for CD40, CD40LG andBAFF polymorphisms in pemphigus finds support in studies ofprotein or mRNA levels in PF and PV, and in the effects of these molecules andtheir genetic variants in homeostasis, in inflammation, and ADs." (PMID 32639508, 2020). "Involvement of CD40/CD40LG levels was observed in the pathogenesis of pemphigus.Upregulation of both the receptor and the ligand has been reported in lesionalskin and the serum of patients with active PV and PF." (PMID 32639508, 2020).
lung adenocarcinoma (13 papers, 2010 to 2025). A carcinoma that arises from the lung and is characterized by the presence of malignant glandular epithelial cells. "The GM.CD40L is another allogenic vaccine composed of radiated lung adenocarcinoma cells transduced with the GM-CSF and CD40-ligand (CD40L) genes." (PMID 29329556, 2018). "The aim of this study is to investigate the effect of soluble CD40 ligand (sCD40L) combined with vinorelbine on lung adenocarcinoma cell line A549." (PMID 20673484, 2010).
dermatitis (12 papers, 2004 to 2026). An inflammatory process affecting the skin. "Other biomarkers under investigation are angiopoietin-1 (Ang-1) and CD40 ligand, whose baseline high levels have been related to dermatitis." (PMID 36900420, 2023).
bladder cancer (11 papers, 2003 to 2025). "Our results also raise the possibility of the future development of CD40- and CD40 ligand-based immunotherapy for bladder cancer." (PMID 12592374, 2003). "Study showed that adenoviral vectors expressing CD40 ligand (AdCD40L) were safe in vivo and could reduce the number of tumor cell infiltration in bladder cancer." (PMID 35193632, 2022).
chronic granulomatous disease (11 papers, 2013 to 2025). Chronic granulomatous disease (CGD) is a rare primary immunodeficiency, mainly affecting phagocytes, which is characterized by an increased susceptibility to severe and recurrent bacterial and fungal infections, along with the development of granulomas. "We also diagnosed two younger patients with diarrhoea as having chronic granulomatous disease (CYBB mutation) and hyper-IgM syndrome (CD40LG mutation)." (PMID 30001197, 2018). "It has also been described in genetically diverse IEIs including ataxia telangiectasia, NFKB1 haploinsufficiency, ADA2 deficiency, CD40 ligand deficiency, activated PI3K delta syndrome, STAT3 gain of function and chronic granulomatous disease (CGD)." (PMID 38068532, 2023).
glioblastoma (11 papers, 2017 to 2025). The most malignant astrocytic tumor (WHO grade IV). "Interestingly, tumor cells expressed the CD40 ligand (CD40L), a positive prognostic factor in glioblastoma." (PMID 33477757, 2021). "In addition, activated platelets in platelet-rich fibrin patches produce soluble CD40 ligand (sCD40L), which inhibits the infiltration of CD4+CD25+Foxp3+ regulatory T cells (Tregs) into the microenvironment of glioblastomas, and plays an important role in suppressing antitumor immunity." (PMID 38689760, 2024).
metastatic melanoma (11 papers, 2012 to 2025). A melanoma that has spread from its primary site to another anatomic site. "In the clinical treatment of metastatic melanoma and bladder tumors, there is an adenovirus-based CD40 ligand (AdCD40L) gene therapy in which CD40L interacts with CD40 to promote an adjuvant T-cell 1 (Th1) immune response, leading to T-cell activation and migration to the TME." (PMID 40216744, 2025).
neuroblastoma (11 papers, 2003 to 2025). Neuroblastoma (NB) is the most common solid, extracranial childhood tumor. "For example, the murine gene for CD40 ligand (CD40L) was introduced into murine neuroblastoma tumor cells using a retrovirus as a gene delivery vehicle." (PMID 26561829, 2015).
thalassemia (11 papers, 2010 to 2025). An inherited blood disorder characterized by a decreased synthesis of one of the polypeptide chains that form hemoglobin. "The association between soluble CD40 ligand and the frequency of pain episodes in the past year in the SS/SD/Sβ0 thalassemia group suggests that platelet activation may contribute to the pathogenesis of acute pain episodes in SCD." (PMID 22253781, 2012).
cervical carcinoma (10 papers, 2011 to 2025). A carcinoma arising from either the exocervical squamous epithelium or the endocervical glandular epithelium. "One possible explanation is that the platelet release CD40 ligand and gingival fibroblasts expressing the respective CD40 receptor, upon activation, drive cytokine but presumably also chemokine production, as reported for cervical carcinoma cells." (PMID 41009676, 2025). "AKNA directly binds the A/T-rich promoters regions of CD40 and CD40 ligand (CD40L) and coordinately regulates their expression, thereby activate antitumor immune response, while HPV E6, a cervical cancer-related oncoprotein, could downregulate AKNA and lead to the progression of cancer." (PMID 32462010, 2020).
systemic sclerosis (10 papers, 2003 to 2024). A chronic disorder, possibly autoimmune, marked by excessive production of collagen which results in hardening and thickening of body tissues. "The aim of the present study was to investigate the possible role of CD40 and CD40 ligand (CD40LG) genes in the susceptibility and phenotype expression of systemic sclerosis (SSc)." (PMID 22731751, 2012). "Similarly, in female patients with systemic sclerosis, overexpression of CD40LG transcripts and proteins in CD4T cells was linked to reduced DNA methylation in the CD40LG promoter and enhancer regions." (PMID 39256355, 2024). "In systemic sclerosis (SSc) CD40LG is overexpressed, which sets up an overly sensitive response." (PMID 25763008, 2015).
cognitive decline (9 papers, 2008 to 2025). "Studies have shown that an increase in peripheral pro-inflammatory markers such as C-reactive protein (CRP), Interleukin-6 (IL-6) and soluble CD40 ligand (sCD40L) accompanies cognitive decline." (PMID 37686198, 2023).
diabetic nephropathy (9 papers, 2009 to 2022). "It is reported that soluble CD40 ligand and platelet surface bio-factors are correlated with diabetic nephropathy." (PMID 28376867, 2017).
cryptosporidiosis (7 papers, 2009 to 2025). Intestinal infection with organisms of the genus Cryptosporidium. "The patient diagnosed with CD40 ligand deficiency, sclerosis cholangitis, and prolonged cryptosporidiosis required bone marrow transplant as well as liver transplant after GVHD intended for the full immune reconstruction." (PMID 29946765, 2018).
diabetic retinopathy (7 papers, 2015 to 2026). "Combined with previous research, this finding suggests the potential involvement of the CD40 ligand in diabetic retinopathy pathogenesis from the onset." (PMID 37959396, 2023).
experimental autoimmune encephalomyelitis (7 papers, 2010 to 2020). An autoimmune demyelinating disease of the central nervous system that is produced experimentally in animals by the injection of homogenized brain or spinal cord in Freund's adjuvant. "The physiological relevance of CD40/CD40-ligand in Th17-cell differentiation has been recently proven using a mouse model of experimental autoimmune encephalomyelitis and Cd40−/− mice were found to be protected from the disease." (PMID 20634952, 2010).
T-cell lymphoma (7 papers, 2012 to 2024). "The expression levels of CD28 and CD40LG are tightly regulated in normal T cells, as abnormal activation or overexpression of them lead to many types of T-cell malignancies including ATLL and T-cell lymphomas." (PMID 38233409, 2024). "Secondly, CD28 and CD40LG are two essential stimulatory molecules expressed on the surface of T cells; aberrant overexpression or activation of them contribute to many types of T-cell malignancies including adult T-cell leukemia/lymphoma (ATLL) and T-cell lymphomas." (PMID 38233409, 2024).
Zinc deficiency (7 papers, 2014 to 2025). A deficiency of the essential metal Zinc; an essential cofactor for many enzymes. "We demonstrated that the activation of the CD40 ligand (CD154)‐induced p38 MAPK was negatively affected by cellular zinc deficiency in Raji B lymphocytes while zinc supplementation had little influence on the activity of p38 MAPK when cellular zinc was replete." (PMID 28469980, 2017).
Thrombocytosis (6 papers, 2011 to 2025). Increased numbers of platelets in the peripheral blood. "Among the causes of thrombocytosis is the capability of some tumor cells to produce thrombopoietin, and an upregulation of the platelet activation markers, such as P-selectin, β-thrombomodulin, or CD40 ligand, contributing to an increase in the platelet count." (PMID 35008814, 2021).
allergic rhinitis (5 papers, 2020 to 2024). Inflammation of the nasal mucous membranes caused by an IgE-mediated response to external allergens. "Targeting the CD40/CD40 ligand (CD154) interaction by CD40 siRNA given to bone-marrow-derived DCs attenuated allergic rhinitis and induced the conversion of CD4+ T cells into regulatory T cells." (PMID 31991941, 2020).
autoimmune encephalitis (5 papers, 2008 to 2025). Inflammation of the brain secondary to an immune response triggered by the body itself. "For example, experimental autoimmune encephalitis model seems to largely support an adaptive, antigen presenting activation of encephalitogenic T cells in the presence of the CD40-CD40 ligand interaction." (PMID 18478117, 2008).
Pneumocystis jirovecii pneumonia (5 papers, 2018 to 2024). "We thus investigated whether transplantation of increasing proportions of WT HSPC or adoptive transfer of WT CD4 T cells into Cd40lg−/− mice would confer protection against the mouse model of Pneumocystis pneumonia." (PMID 33475257, 2021).
acute chest syndrome (4 papers, 2012 to 2024). A vaso-occlusive crisis of the pulmonary vasculature occurring in patients with sickle cell disease. "Soluble CD40 ligand (sCD40L) is elevated in SCD and increases during a crisis and in patients with acute chest syndrome." (PMID 33763072, 2021).
glaucoma (4 papers, 2008 to 2024). Increased pressure in the eyeball due to obstruction of the outflow of aqueous humor. "Three hub genes, CD40LG, TEK, and MDK, were validated as potential diagnostic biomarkers for high-risk glaucoma patients, showing increased expression in the NMDA-induced excitotoxicity model." (PMID 38694874, 2024). "The research did not directly find a connection between CD40LG and glaucoma or its clinical implications for treatment." (PMID 38694874, 2024).
Hypoglycemia (4 papers, 2015 to 2023). A decreased concentration of glucose in the blood. "%Change of CD40LG was higher at 24 h post-hypoglycemia in T2D in mild-hypo (20.0 ± 20.0 vs. -6.4 ± 2.8%change of CD40LG at 24 h post-hypoglycemia in T2D, study-1 vs. study-2, p = 0.033)." (PMID 36203210, 2022). "Mild-hypo increased the %change of CD40LG in T2D (49.3 ± 29.3 vs. 6.8 ± 4.6%change of CD40LG at hypoglycemia, study-1 vs. study-2, p = 0.014)." (PMID 36203210, 2022). "By 24-hours, in T2D, CD40LG continued to show increased %change in milder prolonged hypoglycemia; vWF emerged at this timepoint similarly showing increased %change in milder prolonged hypoglycemia." (PMID 36203210, 2022). "From baseline to hypoglycemia, %change differences between studies were seen in PRPs for both T2D (PAI-1, CD40LG, GPVI, tissue factor) and controls (PAI-1, CD40LG, Protein S, vWF); two proteins being common (PAI-1, CD40LG)." (PMID 36203210, 2022). "Hypoglycemia can induce an inflammatory response, including mobilization of leukocytes, an increase in cluster of differentiation 40 (CD40) expression on mononuclear cells, plasma soluble CD40 ligand (sCD40L) levels and platelet-monocyte aggregation." (PMID 37298308, 2023).
renal cell carcinoma (4 papers, 2021 to 2025). "The cross-linking of CD40 by CD40 ligand activates different signaling pathways in renal cell carcinoma cells and in particular can influence proliferation and motility thus playing a possible role also in the development of metastasis." (PMID 34445576, 2021).
viral myocarditis (4 papers, 2014 to 2024). Myocarditis that is caused by an infection with a viral agent. "Anti-CD40LG antibody reduced myocardial inflammation response in mice with acute viral myocarditis." (PMID 28407751, 2017).
colorectal tumor (3 papers, 2021 to 2024). "Further bioinformatic analyses revealed that several immune cell markers, including CCR7, CD40LG, and CD3G, were among the most positively correlated genes with DNASE1L3 in human colorectal tumors, indicative of a possible association between DNASE1L3 expression and antitumor immune activity." (PMID 37581941, 2023).
HELLP syndrome (3 papers, 2022 to 2024). A life-threatening condition that can potentially complicate pregnancy. "In case of HELLP syndrome, only one common target (CD40LG, the gene encoding the CD40 ligand) associated with cardiovascular risk factors and cardiovascular diseases was identified." (PMID 39296937, 2024).
Mitral stenosis (3 papers, 2020 to 2025). An abnormal narrowing of the orifice of the mitral valve. "Moreover, only one study has assessed plasma levels of soluble CD40 ligand (sCD40L), reporting higher concentrations in RHD patients with moderate-to-severe mitral stenosis compared to healthy controls." (PMID 41305420, 2025).
biliary tract disease (2 papers, 2022 to 2023). "Up to one third of patients with CD40L deficiency have liver involvement, with Cryptosporidium-related gastrointestinal and/or biliary tract disease affecting between 6 and 21% of CD40 ligand deficiency patients." (PMID 38068532, 2023).
familial Mediterranean fever (2 papers, 2025). Familial Mediterranean fever (FMF) is an autoinflammatory disorder characterized by recurrent short episodes of fever and serositis resulting in pain in the abdomen, chest, joints and muscles. "In this study, we investigated plasma soluble CD40 ligand (sCD40L) levels and their association with carotid intima–media thickness (cIMT) in children with Familial Mediterranean fever (FMF)." (PMID 40361895, 2025).